APMAP (adipocyte plasma membrane associated protein)
Diseases named in the same sentence as APMAP in open-access papers (continued):
Sharing a sentence is not in itself a finding about the gene and the disease.
lymphoma (1 paper, 2024). A malignant (clonal) proliferation of B- lymphocytes or T- lymphocytes which involves the lymph nodes, bone marrow and/or extranodal sites. "In addition, one recent in vitro CRISPR screen has identified GPR84 as an enhancer for phagocytosis of Ramos lymphoma cells; which can be escaped by overexpression of adipocyte plasma membrane-associated protein (APMAP)." (PMID 38349405, 2024).
memory impairment (1 paper, 2019). "To investigate at the molecular level the neurobiological functions of APMAP (memory and Aβ formation) and a possible link with the pathological hallmarks of AD (memory impairment and Aβ pathology), we next developed a procedure for the high-grade purification of cellular APMAP protein complexes." (PMID 30704515, 2019).
metastatic colorectal cancer (1 paper, 2015). "Expression of APMAP was reported to be strongly correlated with hepatic-specific metastasis in patients with metastatic colorectal cancer." (PMID 25628020, 2015).
Senile plaques (1 paper, 2019). Senile plaques are extracellular deposits of amyloid in the gray matter of the brain. "Altogether, our findings revealed subtle but important roles of APMAP in the learning and memory processes and in the production of Aβ peptides and their deposition into senile plaques." (PMID 30704515, 2019). "In a mouse model of AD, the constitutive deletion of APMAP worsened the spatial memory phenotype and led to increased Aβ production and deposition into senile plaques." (PMID 30704515, 2019). "We also demonstrate that the lack of APMAP increased the production of Aβ peptides and their aggregation into senile plaques in the hippocampus of an AD mouse model." (PMID 30704515, 2019).
Stroke (1 paper, 2025). Sudden impairment of blood flow to a part of the brain due to occlusion or rupture of an artery to the brain. "Shared DEGs between AIS and CIS, including genes such as KIF5B, C4orf3, APMAP, and STOML1, may reflect common molecular signatures associated with stroke across different clinical stages." (PMID 41356252, 2025). "Regional MSN differences were associated with cortical transcriptional gradients, identifying key stroke-related genes (e.g., KIF5B, C4orf3, APMAP, STOML1)." (PMID 41356252, 2025).
uterus cancer (1 paper, 2019). "A TCGA UCEC project (uterus cancer) sample A2HD harbored a G > A silent (synonymous) variant (chr20:24949636) in exon 8 of the APMAP gene." (PMID 31631560, 2019).
cancer (12 papers, 2015 to 2025). A tumor composed of atypical neoplastic, often pleomorphic cells that invade other tissues. "Loss of the APMAP gene can significantly enhance the macrophage phagocytosis of cancer cells, which is dependent on GPR84 and Gi12." (PMID 37709767, 2023). "Using the whole genome screen of macrophages, they found that the G-protein coupled receptor GPR84 enhanced phagocytosis of APMAP-deficient cancer cells." (PMID 37427373, 2023). "Loss of APMAP in cancer cells was shown to synergize with monoclonal antibody therapy and sensitize multiple tumor models to macrophage phagocytosis." (PMID 36479127, 2022). "In addition to known factors such as CD47, they have identified many ADCP sensitive regulators in cancer cells, including adipocyte plasma membrane associated protein (APMAP) enzymes which was poorly characterized." (PMID 37427373, 2023). "This study identified an enzyme expressed in cancer cells named APMAP (Adipocyte Plasma Membrane Associated Protein) that functions as an anti-phagocytic factor to impede antibody-dependent cellular phagocytosis (ADCP) of cancer cells induced by blocking CD2012." (PMID 37709767, 2023). "Our study provides a plausible explanation for the roles of CRELD2 and APMAP in cancer cells undergoing ER stress." (PMID 40821803, 2025). "APMAP was mainly expressed in lymphocytes and cancer cell, SPI1 was highly expressed in macrophages, and ADAM10 showed high expression in cancer cell and lymphocytes, indicating their potential roles in tumor immunity and microenvironment regulation." (PMID 40396172, 2025). "Future studies focusing on the APMAP-GPR84 axis will shed more light on APMAP’s potential as an independent innate immune checkpoint in cancer." (PMID 36135216, 2022). "Studies have shown that APMAP plays important biological roles in fat differentiation, cancer development, viral infections, Alzheimer's disease, and so on 15, 18-20." (PMID 34539899, 2021). "The human APMAP has been reported to be involved in a variety of biological processes including adipocyte differentiation, hepatic-specific metastasis in cancer, and inhibition of Aβ production." (PMID 25628020, 2015). "However, the functional roles and molecular mechanisms of APMAP remains poorly understood in cancer research, particularly in ESCC." (PMID 40821803, 2025). "In addition, the membrane-embedded enzyme APMAP that is highly expressed on the surface of cancer cells has been proposed to degrade the physiological lipid ligand of GPR84 to negatively regulate macrophage phagocytosis." (PMID 37709767, 2023). "The APMAP mRNA level was higher in cancer tissues than in normal cervical tissues (P < 0.05)." (PMID 34539899, 2021). "In a study published in Nature, researchers used intercellular CRISPR screening to identify PRFs in cancer cells, and using genome-wide reverse screening in macrophages, they found that the G-protein-coupled receptor GPR84 mediates enhanced phagocytosis in APMAP-deficient cancer cells." (PMID 35706452, 2022). "However, follow-up studies are required to establish the mechanism by which APMAP may regulate antibody-dependent phagocytoses of cancer cells." (PMID 36135216, 2022). "They further found that the deletion of APMAP combined with tumor antigen targeted monoclonal antibodies and/or CD47 blocking antibodies, significantly increase phagocytosis in a wide range of cancer cell types." (PMID 37427373, 2023). "Identifying such a ligand of GPR84 and APMAP may lead to the identification of a novel pathway regulating macrophage function and facilitate the development of novel therapeutics targeting this pathway in addition to GPR84 activators to enhance cancer cell phagocytosis." (PMID 37709767, 2023).
tumor (9 papers, 2017 to 2025). "Notably, the critical role of specific N‐glycosylation at N196 of Adipocyte plasma membrane‐associated protein (APMAP) is highlighted, a key player in tumor metabolism and CRC progression, providing a potential target for therapeutic intervention." (PMID 40285620, 2025). "Moreover, a novel gene, adipocyte plasma membrane-associated protein (APMAP), traditionally associated with white adipose tissue differentiation but not previously associated with phagocytosis, was discovered to strongly desensitize tumor cells to ADCP." (PMID 35865547, 2022). "We found that APMAP.N196.4200 is significantly reduced in tumor tissues and promotes CRC cell proliferation and migration in vitro." (PMID 40285620, 2025). "Interestingly, as for another protein of this category, APMAP, our data show that IFN-γ expression was minimal in this tumor." (PMID 29662647, 2018). "Notably, the overexpression and methylation patterns of APMAP, IQGAP2, and FASN in LAR cell lines support a hypothesis of epigenetically regulated tumor cell expression that is retained despite in vitro culturing." (PMID 40155623, 2025).
infection (4 papers, 2018 to 2022). The state of being infected such as from the introduction of a foreign agent such as serum, vaccine, antigenic substance or organism. "There is also some evidence that adipocyte plasma membrane-associated protein (APMAP) facilitates JCPyV (genotype 1) infection, though it is unclear whether it facilitates attachment or entry." (PMID 35746603, 2022). "APMAP is an N-linked glycosylated type I transmembrane protein found in a variety of tissue types and could be an interesting avenue of research regarding JCPyV receptor-mediated infection in the brain." (PMID 35746603, 2022). "Accordingly, the expression levels of HCMV proteins pp65, gH, and gO were lower in infected APMAP K/O cells compared to that in infected wildtype and vector-control cells at 72 h after infection." (PMID 31356650, 2019). "The infected APMAP O/E MDCK cells or APMAP O/E NIH/3T3 cells also produced more infectious virions than corresponding infection in wildtype and vector control cells." (PMID 31356650, 2019). "Enhanced HCMV entry led to increased IE mRNA transcription in the APMAP O/E cells, which is a prerequisite for initiation of lytic infection cycle." (PMID 31356650, 2019). "Meanwhile, infection of the APMAP modified cells with herpesvirus simplex virus 2 (HSV-2) showed that deficiency in or overexpression of APMAP did not consistently affect HSV-2 infection in the tested cell lines." (PMID 31356650, 2019). "Consistent with higher viral mRNA detected at 8 h post infection in APMAP O/E ARPE-19 cells, the western blot assay also showed that expression of viral proteins pp65, gH, and gO in APMAP O/E ARPE-19 cells at 72 h post infection were slightly higher than those in the wildtype and control cells." (PMID 31356650, 2019). "Interestingly, the number of GFP positive cells significantly increased in APMAP O/E cells than in control cells at 48 h post infection by either AD169-GFP or AD169rev-GFP (MOI = 1.0)." (PMID 31356650, 2019). "In contrast, depletion of two other identified proteins, adipocyte plasma membrane-associated protein (APMAP) and cleft lip and palate transmembrane protein 1 (CLPTM1), led to an increase of infection by over 70%, indicating that these factors restrict viral entry under physiological conditions." (PMID 29666374, 2018). "Furthermore, reduction in viral immediate early (IE) gene transcription at 6 h post infection and delayed nucleus translocation of tegument delivered pp65 at 4 h post infection were detected in APMAP-deficient cells but not in the wildtype cells." (PMID 31356650, 2019). "At 48 h after infection with AD169rev-GFP, the number of GFP positive cells among the APMAP K/D cells were significantly lower (up to 70%) than that in wildtype HepG2 cells and cells with sc-shRNA." (PMID 31356650, 2019). "At 48 h post infection, the numbers of GFP positive cells among AD169-GFP and AD169rev-GFP infected APMAP K/D cells were significantly lower than that of infected sc-shRNA control and wildtype MRC-5 cells." (PMID 31356650, 2019). "Consistently, viral IE mRNA and pp65 mRNA levels were also significantly higher in APMAP O/E MDCK cells than in wildtype and vector control cells after infection by AD169-GFP and AD169rev-GFP." (PMID 31356650, 2019). "The number of cells with GFP expression at 72 h post infection was also significantly lower in APMAP K/D cells than that of control cells for both AD169-GFP and AD169rev-GFP infection." (PMID 31356650, 2019). "Collectively, these results show that over expression of APMAP in ARPE-19 cells slightly enhanced infection by HCMV strains with and without pentamer, which led to enhanced transcription of viral genes and expression of viral proteins." (PMID 31356650, 2019).
APMAP also shares sentences with these, for which no sentence is quoted: amyloid diseases (1 paper); demyelinating disease (1); dysphoria (1); esophageal squamous cell carcinoma (1); gestational diabetes mellitus (1); Hallucinations (1); insomnia (1); musculoskeletal disorders (1); primary Sjogren’s syndrome (1).